CETP (cholesteryl ester transfer protein)
Diseases named in the same sentence as CETP in open-access papers (continued):
Sharing a sentence is not in itself a finding about the gene and the disease.
lung carcinoma (2 papers, 2022 to 2024). "For lung cancer, we observed a protective effect of lower CETP for lung cancer in East Asians (OR 0.77, 95%CI 0.70; 0.85), with a more uncertain effect in Europeans (OR 1.04 95%CI 0.99; 1.09)." (PMID 38906890, 2024). "The effect of low CETP on lung cancer in Europeans did not rule out a neutral effect however: OR 1.04 (95%CI 0.99; 1.09)." (PMID 38906890, 2024).
migraine (2 papers, 2023 to 2024). "Conversely, CETP inhibition demonstrated a suggestive association with a lower risk of migraine." (PMID 37596566, 2023). "Furthermore, the study identified weak evidence suggesting that CETP inhibition may offer protection against migraines." (PMID 37596566, 2023). "For instance, CETP inhibitors, despite not achieving the expected benefit of reducing cardiovascular disease risk, may warrant further investigation for their effects on migraine occurrence." (PMID 39204161, 2024).
Non-Alcoholic Steatohepatitis (2 papers, 2014 to 2022). "We previously reported that oral administration of Oxy210, a semi-synthetic oxysterol, ameliorates non-alcoholic steatohepatitis (NASH) induced by a high-fat diet in APOE*3-Leiden.CETP humanized mouse model of NASH and inhibits expression of hepatic and circulating levels of inflammatory cytokines." (PMID 35628290, 2022).
ovarian carcinoma (2 papers, 2022). A malignant neoplasm originating from the surface ovarian epithelium. "The role of CETP, CCR7, and SELL in ovarian cancer is less studied." (PMID 36704336, 2022).
pneumonia (2 papers, 2024). An acute, acute and chronic, or chronic inflammation focally or diffusely affecting the lung parenchyma, caused by an infection in one or both of the lungs (by bacteria, viruses, fungi, or mycoplasma.). "Taken together, these results establish that CETP inhibition led to significantly improved survival and less extensive pneumonia in 2 independent mouse models." (PMID 38646937, 2024). "The goals of this study were to investigate the effects and cellular mechanisms of CETP inhibition in a mouse model of pneumonia and in vitro model systems." (PMID 38646937, 2024). "Exploring potential associations with non-cardiovascular outcomes, we observed a protective effect of lower CETP against pneumonia in both Europeans (OR 0.87, 95%CI 0.84; 0.90) and East Asians (OR 0.89, 95%CI 0.81; 0.99)." (PMID 38906890, 2024).
sarcopenia (2 papers, 2022 to 2024). Progressive decline in muscle mass due to aging which results in decreased functional capacity of muscles. "In conclusion, our study provided a serum proteomic profile of sarcopenia patients, and identified two proteins (CETP and APOA2) with diagnostic value." (PMID 36192674, 2022). "Furthermore, the nature of the cross-sectional study was unable to determine a causal relationship between APOA2, CETP and sarcopenia." (PMID 36192674, 2022). "In this study, the level of CETP was up-regulated in early sarcopenia OAs group." (PMID 36192674, 2022). "The PPI network further suggested that the cholesteryl ester transfer protein and Apolipoprotein A2 could serve as biomarkers to facilitate diagnosis of sarcopenia." (PMID 36192674, 2022). "In addition, the diagnostic value of CETP and APOA2 in sarcopenia and whether they could be used as therapeutic targets need further research." (PMID 36192674, 2022). "Moreover, P11597 (CETP) and P02652 (APOA2) were involved in multiple biological processes, suggested that these two proteins played an important role in the progression of sarcopenia and had potential diagnostic value." (PMID 36192674, 2022). "We noticed that, compared with the healthy group, the expression levels of J3KPA1 (CRISP3), P11597 (CETP), and P14780 (MMP9) were up-regulated in the early sarcopenia group, while the expression levels of the other 6 proteins were down-regulated." (PMID 36192674, 2022). "In contrast to CETP, the level of APOA2 was down-regulated in early sarcopenia OAs group." (PMID 36192674, 2022).
schistosomiasis (2 papers, 2014 to 2021). An infectious disease caused by parasitic trematodes of the genus Schistosoma that colonize human blood vessels and release eggs that can cause granulomatous reactions leading to acute (swimmer's itch or acute schistosomiasis syndrome) or chronic disease. "For example, we have reported LCAT deficiency in human and animal schistosomiasis, while decreased CETP activity is a feature of the acute-phase response and raises HDL levels, particularly ApoE-rich HDL." (PMID 25051269, 2014). "Although there is no explanation for these divergent results, it is possible to conjecture that the role of CETP could also depend on the animal species and pathology involved since CETP inhibition protects against hepatic complications in Schistosomiasis japonicum." (PMID 34367144, 2021).
acute pancreatitis (1 paper, 2022). An acute inflammatory process that leads to necrosis of the pancreatic parenchyma. "After correcting for outliers, 1 SNP (CETP gene) was removed in acute pancreatitis." (PMID 36299997, 2022).
artery disease (1 paper, 2024). "Inline with our expectations, our genetically proxied instruments forPCSK9, HMGCR, CETP and APOC3 in the Mendelianrandomization analysis demonstrated a noteworthy reduction in susceptibility tocoronary artery disease." (PMID 39228495, 2024).
cardiac hypertrophy (1 paper, 2024). "Re improved cardiac hypertrophy mainly associated with the inhibition of mRNA level and protein expression of CETP, to an extent comparable to that of the classical CETP inhibitor, anacetrapib." (PMID 38854305, 2024).
cerebrovascular diseases (1 paper, 2022). "Some clinical trials also have shown that some drugs that increase HDL-C levels, such as cholesteryl ester transfer protein (CETP) inhibitors and niacin, cannot decrease the risk of cardiovascular and cerebrovascular diseases." (PMID 35717187, 2022).
chronic hepatitis C virus infection (1 paper, 2018). Chronic form of hepatitis C infection. "For instance, it has been shown that subjects with chronic hepatitis C virus infection have elevated serum CETP levels." (PMID 29802315, 2018).
colitis (1 paper, 2025). Inflammation of the colon. "As expected, CETP-Tg mice treated with evacetrapib showed a better colitis outcome, with less weight loss and longer colon length." (PMID 40484317, 2025). "Moreover, subchronic and acute pharmacological inhibition of CETP improved colitis outcome in a mouse model and was associated with changes in inflammatory macrophage markers and gut barrier function." (PMID 40484317, 2025). "We observed that CETP inhibitor (CETPi) with evacetrapib more effectively increased HDL levels and ameliorated colitis in the context of an HFD." (PMID 40484317, 2025). "That is, evacetrapib consistently improved colitis outcome in both CETP-Tg mice and WT mice regardless of diet via selectively increasing HDL-C." (PMID 40484317, 2025).
colorectal cancer (1 paper, 2024). A primary or metastatic malignant neoplasm that affects the colon or rectum. "Furthermore, a clinical study found increased CETP in colorectal cancer patients." (PMID 39193372, 2024).
cutaneous leishmaniasis (1 paper, 2024). Leishmaniasis affecting the skin. "We evaluated the impact of the presence of CETP on infection by Leishmania (L.)amazonensis in an experimental model of cutaneous leishmaniasis using C57BL6/J mice transgenic for human CETP (CETP), having as control their littermates that do not express the protein, wild-type (WT) mice." (PMID 38966642, 2024).
endometrial cancer (1 paper, 2014). Primary or metastatic malignant neoplasm involving the endometrium (mucous membrane that lines the endometrial cavity). "Meta-analysis of the associations between CETP rs708272 (G>A) and rs1800775 (C>A) polymorphisms and endometrial cancer risk." (PMID 24533069, 2014).
endometrioid carcinoma (1 paper, 2024). "Among the six lipid-lowering drug targets, we observed a significant association between lower predicted APOB levels and higher CETP levels with an increased risk of endometrioid carcinoma." (PMID 39193372, 2024). "In drug target Mendelian randomization, genetic modeling of apolipoprotein B (APOB) (OR [95%CI]=0.31, [0.16-0.60]; p=4.73e-04) and cholesteryl ester transfer protein (CETP) (OR [95%CI]=1.83, [1.38-2.43]; p=2.91e-05) genetic mimicry was associated with non-endometrioid carcinoma." (PMID 39193372, 2024).
Erythema (1 paper, 2022). Redness of the skin, caused by hyperemia of the capillaries in the lower layers of the skin. "Consistent with a previous report, IMQ-induced psoriatic lesions, such as scaling, erythema, acanthosis, thickening, neoangiogenesis, and inflammatory infiltrates, appeared in WT mice and CETP-Tg and PLTP-Tg mice." (PMID 35982498, 2022). "Five consecutive days following the initiation of IMQ use, CETP-Tg and PLTP-Tg mice’s back skin displayed more signs of erythema, thickening, and scaling than WT mice." (PMID 35982498, 2022).
fibrosis (1 paper, 2024). the formation of excess fibrous connective tissue in an organ or tissue in a reparative or reactive process. "At 12 weeks, the CETP group showed decrease in inflammation and parasitism, the presence of fibrosis interstitial scar in both the superficial and deep dermis, accompanied by a mild mononuclear infiltrate, absence of giant cells and complete absence of parasitized macrophages." (PMID 38966642, 2024).
gallstones (1 paper, 2021). Solid crystalline precipitates in the biliary tract, usually formed in the gallbladder, resulting in the condition of cholelithiasis. "Elevated activity of cholesteryl ester transfer protein (CETP) in patients with gallstones may lower HDL-c and increase LDL-c by transferring the lipoprotein from HDL to LDL." (PMID 33757439, 2021).
HCMV infection (1 paper, 2017).
Hypocholesterolemia (1 paper, 2024). An decreased concentration of cholesterol in the blood. "Although low HDL-C levels may be a consequence of severe hemolytic anemia, the absence of minor alleles of the CETP gene in patients with SCD also proved to be an explanatory pathway for the observed hypocholesterolemia." (PMID 38265339, 2024).
infertile (1 paper, 2011). "The present study does not clarify the mechanism by which the CETP affect infertility risk status." (PMID 26396563, 2011). "The aim of the present study was to investigate the correlation between CETP level in FF and the success of IVF/ICSI techniques in infertile patients undergoing these techniques." (PMID 26396563, 2011).
Lewy body dementia (1 paper, 2024). A progressive form of dementia characterized by the presence of protein deposits called Lewy bodies in the midbrain and cerebral cortex, and loss of cholinergic and dopaminergic neurons. "Drug target Mendelian randomization (MR) was employed to anticipate the on-target effects of lower CETP concentration (μg/mL) on plasma lipids, cardiovascular disease outcomes, autopsy confirmed Lewy body dementia (LBD), as well as Parkinson’s dementia." (PMID 39415269, 2024).
liver cirrhosis (1 paper, 2010). "Serum CETP, PLTP and LCAT activities in control subjects and patients with liver cirrhosis." (PMID 20470383, 2010).
liver inflammation (1 paper, 2019). "We showed that metabolic liver inflammation, as a histologically determined component of NAFLD in obese individuals, did not associate with CETP measures (i.e. liver CETP, liver CETP positive cells and circulating CETP concentrations)." (PMID 31292457, 2019).
nephrotic syndrome (1 paper, 2020). A collection of symptoms that include severe edema, proteinuria, and hypoalbuminemia; it is indicative of renal dysfunction. "Moreover, in nephrotic syndrome, plasma cholesteryl ester transfer protein (CETP) has been demonstrated to be activated, which leads to the production of immature HDL." (PMID 31963445, 2020).
osteonecrosis (1 paper, 2025). A none disease characterized by death of bone tissue due to a lack of blood supply.
osteophytes (1 paper, 2020). "In addition, ApoE*3Leiden.CETP males showed high scores for both osteophyte formation and synovitis, while females developed almost no osteophytes but demonstrated high synovitis scores and significantly higher plasma cholesterol levels." (PMID 32456298, 2020).
periodontitis (1 paper, 2019). An acute or chronic inflammatory process that affects the tissues that surround and support the teeth. "Furthermore, higher LCAT and cholesteryl ester transfer protein activities after periodontal treatment support the hypothesis of reduced activation of these proteins and reversed cholesterol transport during periodontitis." (PMID 30842338, 2019).
primary biliary cirrhosis (1 paper, 2012). "An increase in CETP has already been described in primary biliary cirrhosis which is consistent with the LTIP decrease observed in our study, making this glycoprotein an attractive novel biomarker candidate for hepatic scarring." (PMID 22761838, 2012).
pulmonary emphysema (1 paper, 2021). A subcategory of chronic obstructive pulmonary disease (COPD). "Here, we evaluated the role of CETP in macrophage polarization and elastase-induced pulmonary emphysema (ELA) in human CETP-expressing transgenic (huCETP) (line 5203, C57BL6/J background) male mice and compared it to their wild type littermates." (PMID 34367144, 2021). "Total cholesterol (C), triglyceride (TG), lipoprotein fractions, cytokines and CETP plasma levels in WT and huCETP mice after elastase-induced emphysema (ELA), or saline (SAL)." (PMID 34367144, 2021). "Considering the importance of macrophages in the development and formation of pulmonary emphysema and its dependence on the microenvironment where they may present an M1 or M2 phenotype, we evaluated the effect of CETP on elastase-induced emphysema (ELA) in CETP Tg and WT mice." (PMID 34367144, 2021). "In the present study, we explored the influence of CETP on the differentiation and function of macrophages as well as COPD pathogenesis in a murine model of elastase-induced pulmonary emphysema." (PMID 34367144, 2021). "Elastase-induced pulmonary emphysema in huCETP mice promotes lung M2-like phenotype with a deleterious effect in experimental COPD, corroborating the in vitro result in which CETP promoted M2 macrophage polarization." (PMID 34367144, 2021).
retinopathy of prematurity (1 paper, 2017). A bilateral retinopathy characterized by neovascularization, scarring, retinal detachment, and eventually blindness. "Estimated haplotype frequencies of the significantly associated variants in CETP, CFH, and FBLN5 genes in retinopathy of prematurity (ROP) and premature controls." (PMID 29312345, 2017).
rheumatoid arthritis (1 paper, 2018). A chronic, systemic autoimmune disorder characterized by inflammation in the synovial membranes and articular surfaces. "It has been well established that impairment of HDL functionality in patients with rheumatoid arthritis is associated with elevation of CETP activity and expression, as in our recent report." (PMID 29854085, 2018).
sickle cell disease (1 paper, 2024). Sickle cell anemias are chronic hemolytic diseases that may induce three types of acute accidents: severe anemia, severe bacterial infections, and ischemic vasoocclusive accidents (VOA) caused by sickle-shaped red blood cells obstructing small blood vessels and capillaries. "Allelic association of variants in the CETP gene with HDL-cholesterol levels in participants with sickle cell disease (n=131)." (PMID 38265339, 2024). "Association of hemoglobin level and CETP variants with the HDL-cholesterol levels in participants with sickle cell disease (n=131)." (PMID 38265339, 2024). "Dominance effects of the SNPs rs3764261, rs183130, and rs247616 of the CETP gene in the lipid profile of participants with sickle cell disease." (PMID 38265339, 2024). "Association of hemoglobin level and absence of the TTA haplotype of the CETP gene with levels of HDL-cholesterol in participants with sickle cell disease (n=131)." (PMID 38265339, 2024).
viral infection (1 paper, 2022). "Thus, CETP upregulation might correlate with the alteration of lipids after viral infection (membrane fusion, vesicles, etc.), or even contribute to the lack of symptomatology in these patients." (PMID 35397534, 2022).